CSF1 (colony stimulating factor 1)
Diseases named in the same sentence as CSF1 in open-access papers (continued):
Sharing a sentence is not in itself a finding about the gene and the disease.
lupus (8 papers, 2016 to 2024). "CSF-1 is implicated in the suppression of glial glutamate transporter activity in the spinal dorsal horn and thermal hyperalgesia in lupus mice." (PMID 38612414, 2024). "Colony-stimulating factor-1 (CSF-1), seen in the renal tubules, has been observed to enter the blood circulation in a lupus-susceptible mouse model, with its levels escalating alongside disease progression." (PMID 39104393, 2024). "Molecular mechanisms underlying the role of CSF-1 in regulating the genesis of chronic pain in lupus mice were further elucidated by experiments demonstrating that CSF-1 regulates glutamatergic synaptic activity by altering glial glutamate transporter activities." (PMID 38612414, 2024). "The role of CSF-1 in the genesis of thermal hypersensitivity in lupus mice was evaluated by measuring the latencies of hind paw withdrawal responses to radiant heat stimuli before and after the intrathecal injection of a CSF-1R inhibitor (GW2580)." (PMID 38612414, 2024). "This enhanced glutamatergic synaptic activity and the resulting chronic pain in lupus mice are attributed to the overproduction of proinflammatory cytokines (such as IL-1β and IL-18), CSF-1, and thrombin, as well as reduced AMPK activity in the same region." (PMID 38612414, 2024). "This study suggests that enhanced CSF-1 signaling activity in the spinal dorsal horn leads to thermal hypersensitivity in lupus mice by releasing IL-1β from microglia and suppressing glial glutamate transporter activity." (PMID 38612414, 2024). "In lupus mice experiencing chronic pain, there was an increased protein expression of CSF-1 in the spinal dorsal horn." (PMID 38612414, 2024). "Particularly, CSF-1 acted as a “master switch” and contributed to monocyte and macrophage phenotypes that was positively related with lupus activity in kidney diseases." (PMID 37876929, 2023).
pancreatic ductal adenocarcinoma (8 papers, 2016 to 2023). An infiltrating adenocarcinoma that arises from the epithelial cells of the pancreas. "CSF-1/CSF-1R blockade has also been shown to reprogram tumour associated macrophages, and enhance the response to checkpoint immunotherapy in a pancreatic ductal adenocarcinoma model." (PMID 35359423, 2022). "Presumably, combining anti-CSF1 treatment with checkpoint blockade such as via anti-PD1 and anti-CTLA4 antibodies may enhance immune cell anti-tumor activity and improved efficacy over single-agent treatment as was demonstrated in established pancreatic ductal adenocarcinoma tumors." (PMID 31552020, 2019). "Moreover, blockade of CSF1/CSF1R signaling by GW2850 and PLX3397 CSF1R inhibitors or by anti-CSF-1 not only blocked TAM and M-MDSC recruitment, but also killed CD206high TAMs and reprogrammed the remaining TAMs to support anti-tumor immune activities in murine ductal pancreatic adenocarcinoma." (PMID 27886105, 2016).
Parkinson disease (8 papers, 2007 to 2025). A progressive degenerative disorder of the central nervous system characterized by loss of dopamine producing neurons in the substantia nigra and the presence of Lewy bodies in the substantia nigra and locus coeruleus. "Increased proinflammatory cytokine levels and increased CSF1 have been found in Parkinson’s disease (PD) patients." (PMID 32801364, 2020). "Previous studies have shown that CSF1 improved memory deficits after AD, reduced motor behavioral deficits of Parkinson’s disease, and ameliorated EAE symptoms." (PMID 32522286, 2020). "Although direct evidence supporting enhanced CSF1R expression in activated microglia due to a higher demand for CSF1 is lacking, an overall CSF1R upregulation has been observed in mouse models of amyloidosis and neurotoxic models of Parkinson's disease (Murphy Jr." (PMID 39571180, 2025). "In addition, the lack of CSF-1 does not appear to affect CD200 expression by neurons but we did note a decrease in the substantia nigra of op/op and WT mice, suggesting that this may be a mechanism by which microglia control may be attenuated in this specific area during Parkinson's disease." (PMID 18093340, 2007).
amyloid (7 papers, 2011 to 2025). "To this end, we peripherally injected Cx3cr1CreERT2R26Confetti5×FAD+ mice and controls with the CSF1R ligands Csf1 or interleukin (IL)-34 at early stages of amyloid pathology." (PMID 40659845, 2025). "CSF-1 treatment has been shown to improve memory deficits and ameliorate amyloid plaque burden in the APP/PS1 mice." (PMID 31822279, 2019). "In contrast, downregulation of CSF1 in CAA might reflect an insufficient astrocytic support to cerebral vessels, leading to vascular pathology and possibly exacerbating amyloid accumulation." (PMID 39571157, 2024). "However, CSF-1 treatment in the hAPP mouse model of AD improved cognitive function without altering amyloid deposition." (PMID 31822279, 2019). "In sum, Csf1 treatment, but not IL-34 application, enhances phagocytic capacity of PAM and ameliorates PAM expansion at early stages of disease, thereby facilitating restriction of amyloid pathology." (PMID 40659845, 2025). "Our data support the hypothesis that CSF1R engagement by Csf1 critically modulates microglial subsets and transcriptional states in amyloid pathology by reshaping the functionality of the non-PAM–PAM axis, reducing clonal expansion around the amyloid plaque and enhancing phagocytic activity." (PMID 40659845, 2025).
asthma (7 papers, 2015 to 2024). "In this study, we found that airway CSF1 was significantly elevated in patients with asthma, especially in asthma with a severe and eosinophilic phenotype, and increased CSF1 was associated with increased asthmatic airway eosinophil inflammation." (PMID 37249291, 2023). "Our results showed that both CSF1 and its receptor were significantly increased in asthma compared to healthy participants." (PMID 37249291, 2023). "In this investigation, we determined the expression of CSF1 and its mechanism role in allergen asthma." (PMID 37249291, 2023). "To further confirm CSF1 expression in patients with asthma from a clinical perspective, we prospectively recruited 25 healthy controls and 72 asthmatic patients for PCR and ELISA detection." (PMID 37249291, 2023). "As we found CSF1 was significantly increased in asthma with an eosinophilic phenotype, we further explored the correlation between CSF1 and airway eosinophilic inflammation indicators." (PMID 37249291, 2023). "CSF1, as one of the inflammation‐related genes, plays a critical role in a variety of inflammatory diseases, but there were few reports describing CSF1 expression in the airway and its clinical implications in asthma." (PMID 37249291, 2023). "The expression of CSF1 was significantly increased in patients with asthma compared to healthy controls, especially in patients with severe and eosinophilic asthma." (PMID 37249291, 2023). "In conclusion, elevated airway CSF1 may be involved in the pathogenesis of airway‐increased eosinophil inflammation in asthma." (PMID 37249291, 2023). "The data above indicate that upregulated airway CSF1 may be involved in the airway inflammation of asthma by interacting with its receptor and activating the STAT1 protein." (PMID 37249291, 2023). "Besides, we also detect the mRNA expression of its receptor (CSF1R), our results showed CSF1R was increased in asthma (p = .0144), A positive correlation between CSF1 and CSF1R was observed (rs = 0.4759, p = .0003)." (PMID 37249291, 2023). "Second, the patients in this study were newly diagnosed with asthma (without ICS treatment), and the lack of follow‐up data led to the loss of CSF1 expression in patients with asthma after ICS treatment." (PMID 37249291, 2023). "Furthermore, we enrolled 18 healthy controls and 44 asthma patients to detect the expression of CSF1 protein in the supernatant of induced sputum by ELISA." (PMID 37249291, 2023). "Graphical abstract: Potential regulatory mechanism of CSF1 in asthma." (PMID 37249291, 2023). "In this study, we aimed to explore the expression and its potential mechanism of CSF1 in asthma." (PMID 37249291, 2023). "The link between colony‐stimulating factor 1 (CSF1) and asthma was reported recently." (PMID 37249291, 2023). "The findings indicated that CSF1 may exert its modulatory role by activating CSF1R in the airway pathogenesis of asthma." (PMID 37249291, 2023). "We previously studied CSF1, a key gene in asthma in the induced sputum from the GSE76262 data set." (PMID 37249291, 2023). "CSF1R, the receptor for CSF1, was reportedly involved in the pathogenesis of asthma." (PMID 37249291, 2023). "The data above showed elevated airway CSF1 may play a critical role in the pathogenies of asthma." (PMID 37249291, 2023). "However, the role and mechanism of CSF1 in asthma remain poorly understood." (PMID 37249291, 2023). "It has been reported that airway epithelial cell‐derived CSF1 and CSF1R be involved in the pathogenesis of asthma, especially in the activation of dendritic cells (DCs) and subsequent allergic inflammation." (PMID 37249291, 2023). "In our previous pilot study, we found that sputum CSF1 played a key role in asthma based on GSE76262, subsequent multiomics analysis showed that CSF1 messenger RNA (mRNA) was significantly upregulated in severe and eosinophilic asthma." (PMID 37249291, 2023).
brain tumor (7 papers, 2013 to 2022). "In skin and brain tumor models, neutrophil recruitment was dependent on CXCL8 (IL-8)/CXCR1+2 signaling, while macrophages/microglia were recruited via CSF-1 (M-CSF) and CXCL12b (SDF1b)/CXCR4b pathways." (PMID 35733919, 2022).
cognitive decline (7 papers, 2012 to 2025). "In contrast the type I IFN population which is associated with larger neuroinflammation and cognitive decline in AD may inhibit CSF1-stimulation and cell cycling." (PMID 37332353, 2023). "Elevated salivary IL-34 and CSF-1 levels in AD and MCI patients suggest an inflammatory component linked to cognitive decline." (PMID 40389754, 2025). "In addition, inhibitors targeting receptor of the colony-stimulating factor-1 activity can reduce microglial proliferation and neurodegeneration, slow neuronal damage and disease progression, and prevent cognitive decline in AD." (PMID 36353631, 2022). "Similarly, higher levels of AXL, MERTK, GAS6, LPL, CST7 and CSF1 predicted slower tau accumulation and/or cognitive decline in the A+T+ group." (PMID 37118533, 2022). "Moreover, at an uncorrected level, GAS6 (t = 2.2, P = 0.030) and CSF1 (t = 2.3, P = 0.021) also predicted lower cognitive decline." (PMID 37118533, 2022).
coronary artery disease (7 papers, 2013 to 2023). "Additionally, the latest researches also point to a correlation between blood levels of CSF1 and the risk of coronary heart disease." (PMID 37810795, 2023). "Therefore, we consider the upregulation of CSF1 as the characteristic of PBS syndrome of coronary heart disease." (PMID 36523490, 2022).
helminth infections (7 papers, 2014 to 2024). "It has been demonstrated that stimuli such as CSF-1, IL-4, IL-10, TGF-β, IL-13, fungi, and helminth infections favor M2 subpopulation polarization, delivering IL-10 in high concentrations, and IL-12 in low amounts." (PMID 32258161, 2020). "Alternatively, in response to helminth infection, Th2-dependent production of IL-4 promotes the proliferation of lung-resident macrophages and this proliferation is independent of colony-stimulating factor-1 (CSF-1)." (PMID 25657646, 2014).
metastatic disease (7 papers, 2014 to 2025). "We expect that inhibiting TAVO events, potentially by targeting either or both CSF-1 and Tie2 signaling, will improve our ability to increase the survival of both patients with metastatic disease and patients who are likely to develop metastatic disease." (PMID 40646332, 2025). "We noticed in the case of Myc-knockin OS that CSF1 expression was low and had a more aggressive and metastatic tumor." (PMID 37279073, 2023). "In this study, miR-149-3p acted as a regulator that helped prevent the deuteriations of bone tissue that often occur in metastatic tumors by diminishing the function of colony-stimulating factor 1 (CSF1), which is recognized for its role in promoting bone degradation." (PMID 39585048, 2024). "Inhibition of both Tie2 and CSF-1 signaling to prevent TAVO events, along with standard of care therapies, might be an effective way to prevent re-dissemination from both primary and metastatic tumor sites, and allow for better patient survival." (PMID 40646332, 2025).
multiple myeloma (7 papers, 2019 to 2024). "In addition, we also detected strong Csf1 expression in Adipoq+ cells from the control bone marrow (i.e. non-pathologic) acquired from a recent scRNA-seq study examining human multiple myeloma microenvironment." (PMID 36779854, 2023). "These include granulocyte-macrophage colony-stimulating factor (GM-CSF) and macrophage colony-stimulating factor 1 (CSF-1) in AML, and Interleukin-6 (IL-6) in ALL and multiple myeloma (MM)." (PMID 35677056, 2022).
neuroblastoma (7 papers, 2014 to 2025). Neuroblastoma (NB) is the most common solid, extracranial childhood tumor. "Our findings are corroborated by two recent publications in rodent models that showed that IL-6 + sIL-6R can elevate joint sensory neuron firing in vivo and in vitro, as well as elevate Socs3 and Csf1 in a mouse neuroblastoma cell line." (PMID 40373045, 2025). "Administration of CSF1 to mice inoculated with neuroblastoma cells led to an increase in tumor growth followed by an increase in systemic levels of VEGF and increases in tumor angiogenesis." (PMID 25313137, 2014). "Indeed, in a mouse model of neuroblastoma the blockade of CSF-1 (M-CSF)/CSF-1R signaling inhibited MDSC recruitment and improved the response to anti-PD-1 therapy." (PMID 32580431, 2020). "Mice bearing CSF-1 negative neuroblastoma xenografts showed decreased TAM infiltration and angiogenesis, compared to mice with CSF-1 expressing xenografts." (PMID 33381449, 2020).
peripheral nerve injury (7 papers, 2016 to 2024). Injury to a peripheral nerve. "In neuropathic pain induced by peripheral nerve injury, CSF1 is produced and retrograde transported to the spinal cord by sensory neurons." (PMID 27846891, 2016). "As csf1 was reported to be expressed de novo in injured sensory neurons following peripheral nerve injury, sex-specific regulation of csf1 may lead to sex-related differences in susceptibility to neuropathic pain after nerve injury." (PMID 33114670, 2020). "Hub gene Csf1 within module 2, is a cytokine that has been demonstrated the most critical contributor to macrophages expansion in DRG after peripheral nerve injury by acting via Csf1 receptor (Csf1r, within module 2) expressed on macrophages." (PMID 38813203, 2024). "Csf1 is a prominent chemokine involved in the proliferation and polarization of macrophages and microglia with detrimental effects in SCI and peripheral nerve injury." (PMID 34952603, 2021).
diffuse large B-cell lymphoma (6 papers, 2021 to 2025). "Consistent with our analysis, it was reported that CREBBP can alter tumor-associated macrophage polarization via the FBXW7-NOTCH-CCL2/CSF1 axis, resulting in tumor progression in diffuse large B-cell lymphoma." (PMID 39868264, 2025). "Consistently, another study demonstrated that low expression of CREBBP or EP300 inhibits H3K27 acetylation via the FBXW7–NOTCH–CCL2/CSF1 axis to induce the polarisation of tumour-associated macrophages to the M2 phenotype and tumour cell progression in diffuse large B-cell lymphoma (DLBCL)." (PMID 38493218, 2024). "NOTCH signaling mediates M2 polarization of TAMs in diffuse large B cell lymphoma (DLBCL) through the CREBBP/EP300-FBXW7-NOTCH-CCL2/CSF1 pathway." (PMID 35332121, 2022).
Hodgkins lymphoma (6 papers, 2016 to 2024). A heterogeneous group of malignant lymphoid neoplasms of B-cell origin characterized histologically by the presence of Hodgkin and Reed-Sternberg (HRS) cells in the vast majority of cases. "During characterization of a cDNA library from the Hodgkin lymphoma (HL) cell line L-1236, we discovered a new transcript derived from chromosome 1 at the long intergenic non-protein coding RNA 1768 (LINC01768)/colony stimulating factor 1 (CSF1) region." (PMID 31731509, 2019).
inflammatory bowel disease (6 papers, 2016 to 2025). A spectrum of small and large bowel inflammatory diseases of unknown etiology. "The studies of Xiao-Yu Ai confirm that apigenin effectively inhibits inflammatory bowel disease and colitis-associated cancer through decreased levels of the inflammatory cytokines TNF-α, IL-1β, IL-6, MCP-1, and CSF-1 and of COX-2 in tumors." (PMID 36836951, 2023). "PTPRZ1 involvement has been linked to various inflammatory diseases such as inflammatory bowel disease (IBD) and lupus nephritis, where PTPRZ1 expression was found to correlate with IL-34, CSF1, and CSF-1R expression." (PMID 36530919, 2022). "Differential intestinal expression of the macrophage growth factors colony stimulating factor-1 (CSF-1), interleukin (IL)-34, and their shared CSF-1 receptor (CSF-1R) in inflammatory bowel disease (IBD) has been shown." (PMID 27898738, 2016). "Taken together, our findings suggest that inhibition of CSF-1/CSF-1R signaling by JNJ-40346527 may be effective in managing inflammatory bowel disease." (PMID 31710624, 2019).
influenza (6 papers, 2012 to 2024). An acute viral infection of the respiratory tract, occurring in isolated cases, in epidemics, or in pandemics; it is caused by serologically different strains of viruses (influenzaviruses) designated A, B, and C, has a 3-day incubation period, and usually lasts for 3 to 10 days. "Next, we reconstituted Csf2ra–/– mice with CSF2-cFLiMo or CSF1-cBMM to compare their ability to ameliorate influenza-induced morbidity." (PMID 35393945, 2022). "Transplanted CSF2-cFLiMo more efficiently engrafted empty alveolar macrophage niches and protected mice from influenza infection compared with transplanted BM cells cultured with M-CSF (CSF1-cBMM) or CSF1/CSF2-cBMM." (PMID 35393945, 2022). "Upon influenza infection, Csf2ra–/– mice containing CSF1-cBMM–derived alveolar macrophages showed strikingly increased morbidity (i.e., loss of body weight and temperature; O2 saturation) and mortality compared with mice containing CSF2-cFLiMo–derived alveolar macrophages." (PMID 35393945, 2022).
injury (6 papers, 2012 to 2023). Damage inflicted on the body as the direct or indirect result of an external force, with or without disruption of structural continuity. "Inhibitors of microglia through the colony-stimulating factor 1 receptor (CSF-1R), such as PLX5622 and neutralizing colony-stimulating factor 1 (CSF-1) antibody, also reduce microglial activation and proliferation in the spinal dorsal horn after nerve injury and alter pain responses." (PMID 35976535, 2023).